HPSE (heparanase)
Diseases named in the same sentence as HPSE in open-access papers (continued):
Sharing a sentence is not in itself a finding about the gene and the disease.
gastritis (1 paper, 2021). Inflammation of the stomach. "In this study, we report that H. pylori infection promotes up-regulation of heparanase in gastritis, which in turn facilitates the colonization of H. pylori in the gastric mucosa, thereby aggravating gastritis." (PMID 34220822, 2021). "To investigate the specific function of heparanase in H. pylori-infected gastritis, we employed heparanase knockout (HPA-KO) C57BL/6 mice." (PMID 34220822, 2021). "In conclusion, our results indicate that H. pylori infection promotes overexpression of heparanase in gastritis which in turn facilitates the colonization of H. pylori and hence worsens gastritis." (PMID 34220822, 2021). "Heparanase and cytokeratins are co-expressed in mouse and human gastritis tissues, consistent with the pattern of heparanase expression in other inflamed tissues." (PMID 34220822, 2021). "In this study, we report, for the first time, that H. pylori infection promotes the expression of heparanase in gastritis." (PMID 34220822, 2021). "Heparanase, in turn, further promotes the colonization of H. pylori and aggravates gastritis, forming a vicious circle driven by enhanced NFκB and p38-MAPK signaling and the generation of pro-inflammatory and pro-tumorigenic cytokines." (PMID 34220822, 2021). "Heparanase staining co-localized with CD68+ macrophage staining, suggesting that heparanase in human gastritis originates also from macrophages." (PMID 34220822, 2021). "Our results indicate that heparanase promotes M1 polarization of macrophages driven by H. pylori or LPS + INF-γ, resulting in increased expression of pro-inflammatory cytokines such as IL-1β, IL-6 and TNF-α, and further aggravating the severity of gastritis." (PMID 34220822, 2021).
gastrointestinal carcinomas (1 paper, 2015). "Overexpression of heparanase-1 and heparanase-2, along with increased heparanase-1 and cathepsin B activity in plasma, is associated with the diagnosis of gastrointestinal carcinoma." (PMID 25351637, 2015). "Heparanase and cathepsin B analysis may develop into a safer and less invasive novel diagnostic tool for gastrointestinal carcinomas." (PMID 25351637, 2015). "It was also demonstrated that the heparanase-1 levels in the plasma of gastrointestinal carcinoma patients are higher than in the plasma of the control group." (PMID 25351637, 2015). "The aim of this study was to analyze heparanase isoform expression and cathepsin B activity in plasma samples from patients with gastrointestinal carcinomas, compared with healthy individuals (control group)." (PMID 25351637, 2015). "The analysis on heparanase isoforms and cathepsin B in the plasma of patients with gastrointestinal carcinomas that was proposed in the present study revealed that this is a potential new diagnostic tool." (PMID 25351637, 2015). "The results obtained here showed that the level of the active form of heparanase-1 (50 kDa) was significantly higher in the plasma of the gastrointestinal carcinoma patients than in the control group." (PMID 25351637, 2015). "The aim of this study was to evaluate isoforms of heparanase and cathepsin B in plasma samples from patients with primary gastrointestinal carcinoma, in comparison with healthy individuals." (PMID 25351637, 2015). "The protein expression levels in the plasma of the gastrointestinal carcinoma patients was significantly higher than in the plasma of the healthy individuals for all heparanase isoforms." (PMID 25351637, 2015). "The active form of heparanase-1 (50 kDa) presented higher protein expression in the gastrointestinal carcinoma patients than in the control group: respectively, 28.87 ± 9.70 pixels/μg of total protein and 12.06 ± 4.85 pixels/μg of total protein." (PMID 25351637, 2015). "The greater enzymatic action of heparanase-1 in the plasma of the gastrointestinal carcinoma patients corroborates with the higher of protein expression found through Western blot analysis." (PMID 25351637, 2015). "The results demonstrated that the expression of both heparanase isoforms was significantly greater in plasma samples from gastrointestinal carcinoma patients, compared with the control group." (PMID 25351637, 2015). "Thus, the heparanase-1 enzyme activity in the plasma patients with gastrointestinal carcinoma was seen to be approximately twice as much as in the plasma of the unaffected individuals (Student’s t test, P < 0.0001)." (PMID 25351637, 2015).
heart failure (1 paper, 2017). Inability of the heart to pump blood at an adequate rate to meet tissue metabolic requirements. "Presence of latent form of heparanase in the cardiomyocyte leads to the significant shift in the expression of apoptosis-targeted genes, providing an acute cardioprotective effect indicating diversified roles of heparanase in DCM and heart failure pathology." (PMID 28620607, 2017).
idiopathic pulmonary fibrosis (1 paper, 2025). Idiopathic pulmonary fibrosis (IPF) is a nonneoplastic pulmonary disease that is characterized by the formation of scar tissue within the lungs in the absence of any known cause. "In a recent study on idiopathic pulmonary fibrosis (IPF), it was shown that HPSE contributes to IPF progression by promoting M2 macrophage polarization via the PI3K/Akt-autophagy axis." (PMID 41301515, 2025).
Infertility (1 paper, 2025). "Targeted receptor antagonists and selective heparanase inhibitors—shown in preclinical studies to have immunomodulatory and antithrombotic effects—could provide innovative options, particularly in APS-related infertility." (PMID 40981275, 2025).
ischemic disease (1 paper, 2015). Lack of blood supply to an area of the body, resulting in impairment of tissue oxygenation. "Altogether, these data indicate that EXT2, HPSE, and SDC-4 are involved in the proangiogenic effects of LMWF, suggesting that the HS metabolism changes linked to LMWF-induced angiogenesis offer the opportunity for new therapeutic strategies of ischemic diseases." (PMID 26516869, 2015).
keratitis (1 paper, 2023). A corneal disease that is characterized by inflammation of the cornea. "Thus, HPSE expression may play a role in the loss of ocular immune privilege during infection, which results in more severe symptoms leading to keratitis or corneal blindness as previously reported." (PMID 37115924, 2023).
keratoconus (1 paper, 2017). A degenerative, structural disorder of the eye, characterized by a cone-shaped protrusion of the cornea. "In this paper, we investigate the expression patterns of heparanase genes in the keratoconus cornea in comparison to healthy controls." (PMID 29379222, 2017). "In this article, we study the differential expression of heparanase in cornea and tears from keratoconus patients and healthy controls." (PMID 29379222, 2017). "Heparanase transcription was detected in stromal and epithelial cells and appeared upregulated in keratoconus." (PMID 29379222, 2017). "Heparanase catalytic activity was found in tears and displayed a positive correlation with the degree of keratoconus." (PMID 29379222, 2017). "Taking this line, the upregulation of HPSE in keratoconus could be added to the elevated levels of other inflammatory markers to suggest that keratoconus could be, at least in part, an inflammatory condition." (PMID 29379222, 2017). "Taking into account that the tear proteome displays a highly dynamic character, we investigated the levels of heparanase enzymatic activity in tears of keratoconus patients of different grades in an effort to define its use as a biomarker for this eye disorder." (PMID 29379222, 2017).
laryngeal carcinoma (1 paper, 2023). Carcinoma that arises from the laryngeal epithelium. "This emerges from the observation that HPSE is localized within autophagosomes in association with LC3-II in SIHN-013 laryngeal carcinoma cells overexpressing HPSE." (PMID 37508554, 2023).
liver cirrhosis (1 paper, 2021). "UVB irradiation of human skin samples and cultured keratinocytes induced heparanase expression and activity and rats with liver cirrhosis that received partial liver irradiation showed an upregulation of the heparanase proenzyme in liver and serum." (PMID 34681753, 2021).
lung fibrosis (1 paper, 2022). "In addition, it has been proven that HPSE participates in lung fibrosis by regulating EMT, and it probably also has a role in the liver." (PMID 35965510, 2022).
malignant salivary gland tumors (1 paper, 2015). "Salivary heparanase level was an independent predictor in patients with malignant salivary gland tumors." (PMID 26569485, 2015). "In this study, we confirmed that the salivary heparanase levels in patients with malignant salivary gland tumors were significantly higher than those of patients with benign tumors and of healthy donors." (PMID 26569485, 2015). "In our current study, we confirmed that the levels of heparanase in saliva and tumor tissues were significantly higher in patient with malignant salivary gland tumors than in benign tumors and normal controls, by using immunochemistry and ELISAs." (PMID 26569485, 2015). "Furthermore, we evaluated the clinical significance of salivary heparanase levels by analyzing the correlations between the salivary levels of heparanase and clinicopathological parameters and clinical outcomes in patients with malignant salivary gland tumors." (PMID 26569485, 2015). "In addition, we also demonstrated that patients whose saliva contained high levels of heparanase had worse overall survival and disease-free survival, and that salivary heparanase level was an independent prognostic factor in patients with malignant salivary gland tumors." (PMID 26569485, 2015). "In univariate and multivariate Cox proportional analyses, salivary heparanase level [hazard ratio, 2.805; 95% confidence interval (CI), 1.218–6.460; P = 0.015] was identified as an independent predictor of clinical outcome in patients with malignant salivary gland tumors." (PMID 26569485, 2015). "Furthermore, we evaluated the clinical significance of salivary heparanase levels and found that high levels of heparanase in saliva are notably associated with increased lymph node metastasis and poorer TNM stage in patients with malignant salivary gland tumors." (PMID 26569485, 2015).
mastocytoma (1 paper, 2024). A localized tumor composed of sheets of mast cells without atypia. "Recombinant mouse heparanase mimicking both the latent and mature forms (L-Hpse and M-Hpse, respectively) was internalized into mastocytoma MST cells, peritoneal cell-derived mast cells, and bone marrow-derived mast cells." (PMID 38892469, 2024).
mucopolysaccharidosis (1 paper, 2020). A group of autosomal recessive or X-linked inherited lysosomal storage disorders affecting the metabolism of mucopolysaccharides, resulting in the accumulation of mucopolysaccharides in the body. "On the other hand, in different conditions such as mucopolysaccharidosis, and, in particular, Sanfilippo syndrome, which is a neurodegenerative lysosomal storage disease, the use of HPSE inhibitors may impact HPSE action and influence the global distribution of HSPGs." (PMID 31963505, 2020).
myelofibrosis (1 paper, 2019). A partial or complete replacement of the bone marrow stroma by fibrous tissue. "Another key protein, heparanase (HPSE) was previously reported to be present at higher concentrations in PV bone marrow biopsies, is associated with myelofibrosis and displays procoagulant and angiogenic activity." (PMID 31064135, 2019).
nephrotic syndrome (1 paper, 2015). A collection of symptoms that include severe edema, proteinuria, and hypoalbuminemia; it is indicative of renal dysfunction. "The data reported in the present study provide important information on the involvement of heparanase in the pathogenesis of glomerular injury, and extend our previous understanding regarding mechanisms underlying the development of proteinuria in nephrotic syndrome." (PMID 25786136, 2015). "In line with previous reports, we demonstrate an increase of heparanase activity following induction of nephrotic syndrome using Adriamycin in wt control mice." (PMID 25786136, 2015). "Likewise, increased heparanase activity was detected in urine samples from diabetic patients with microalbuminuria, non-diabetic nephrotic syndrome, CKD and kidney transplanted patients." (PMID 25786136, 2015).
neuropathy (1 paper, 2017). A disorder affecting the nervous system that manifests with pain, tingling, numbness, and/or muscle weakness. "Selective blocking heparanase by OGT2115 attenuates cerebrovascular inflammation and prevents SAH-induced neurological impairment, suggesting an involvement of heparanase in SAH-associated neuropathy." (PMID 28720149, 2017). "However, the role of heparanase in SAH-associated neuropathy is still unknown." (PMID 28720149, 2017).
nevus (1 paper, 2016). Nevus (or naevus, plural nevi or naevi, from nævus, Latin for "birthmark") is the medical term for sharply circumscribed[1] and chronic lesions of the skin or mucosa. "In normal epidermal cells as well as non-malignant nevi, heparanase was localized primarily to the cell nucleus (nevus)." (PMID 27732945, 2016).
osteoporosis (1 paper, 2024). A condition of reduced bone mass, with decreased cortical thickness and a decrease in the number and size of the trabeculae of cancellous bone (but normal chemical composition), resulting in increased fracture incidence. "Although unfractionated heparin (UFH), which inhibits heparanase, is known to induce osteoporosis, other lower-molecular-weight heparins that also strongly inhibit heparanase do not exert osteoporosis." (PMID 39766213, 2024).
pleural mesothelioma (1 paper, 2021). A neoplasm that arises from the mesothelial cells of the pleura. "For pleural mesothelioma, downregulation of heparanase enzymes in the tumor microenvironment has been described to result in the formation of a dense extracellular matrix, preventing deep tumor infiltration of viruses and attachment to target cells." (PMID 34696274, 2021).
proliferative diabetic retinopathy (1 paper, 2017). Advanced retinopathy due to diabetes mellitus characterized by the formation of new vessels in the retina. "Increased levels of HPSE have also been related to ocular pathologies, such as the overexpression in corneal epithelium and stroma during infection with Pseudomonas aeruginosa and in the vitreous of patients with proliferative diabetic retinopathy." (PMID 29379222, 2017).
prostatic intraepithelial neoplasia (1 paper, 2016). "Heparanase, an endo-β-D-glucuronidase, is also highly expressed in PCa, especially in metastatic lesions, but not in prostatic intraepithelial neoplasia (PIN)." (PMID 27651838, 2016).
Pseudomonas infection (1 paper, 2017). Infections with bacteria of the genus pseudomonas. "The upregulation of HPSE in cornea associated with Pseudomonas infection has been related to HPSE-positive infiltrating cells, and it was not able to be detected in corneas from immunized mice since they had a lower inflammatory response." (PMID 29379222, 2017).
pulmonary hypertension (1 paper, 2023). Increased pressure within the pulmonary circulation due to lung or heart disorder. "A search using relevant terms, such as “pulmonary hypertension, heparanase, vascular endothelial cells, inflammation, coagulation, glycocalyx, autophagy, exosomes, and fibrosis,” in databases like PubMed and Web of Science reveals the involvement of HPA in pulmonary blood vessels." (PMID 37637421, 2023).
retinopathy of prematurity (1 paper, 2012). A bilateral retinopathy characterized by neovascularization, scarring, retinal detachment, and eventually blindness. "Inhibition of heparanase expression by PI-88 could be used as a novel therapeutic method for retinopathy of prematurity." (PMID 22773903, 2012). "Heparanase expression was upregulated and correlated with an increase in VEGF expression in the OIR mouse retinas, and might be involved in the progress of retinopathy of prematurity." (PMID 22773903, 2012).
retroperitoneal sarcoma (1 paper, 2023). A sarcoma involving a retroperitoneal space. "Heparanase overexpression (driven in human cancers by numerous molecular pathways) is closely associated with enhanced aggressiveness and a poorer prognosis in several types of tumors, notably gastric; colon; ovarian and cervical carcinoma and retroperitoneal sarcoma." (PMID 36979689, 2023).
salivary gland tumors (1 paper, 2015). "Salivary heparanase levels in patients with salivary gland tumors were detected using enzyme-linked immunosorbent assays (ELISAs) and the clinical significance was evaluated by analyzing the correlations among salivary heparanase levels, clinicopathological parameters, and clinical outcomes." (PMID 26569485, 2015). "In our study, we first investigated the levels of heparanase in salivary gland tumor tissues with immunohistochemical staining and found that the heparanase levels in malignant salivary tumor tissues were significantly higher than in benign tumor tissues." (PMID 26569485, 2015). "The study shows that salivary heparanase levels, as detected by the ELISAs, can be used to diagnose and provide an accurate prognosis for malignant salivary gland tumors." (PMID 26569485, 2015). "The levels of salivary heparanase were significantly higher in patients with malignant salivary gland tumors than in benign tumors and normal controls (P<0.0001)." (PMID 26569485, 2015). "In an attempt to find a more simple and sensitive method to differentiate malignant salivary gland tumors from benign tumors, the level of heparanase in saliva was determined by an ELISAs." (PMID 26569485, 2015). "Taken together, our study indicates that salivary heparanase level may serve as a potential biomarker to diagnose and predict malignant salivary gland tumors." (PMID 26569485, 2015). "However, the level of salivary heparanase and its clinical significance in patients with salivary gland tumors remain unclear." (PMID 26569485, 2015). "The intensity of heparanase expression in salivary gland tumors ranged from negative to strongly positive, and the extent of heparanase expression varied from no tumor cells having been stained to more than 90% stained tumor cells." (PMID 26569485, 2015). "However, the variations of salivary heparanase levels in patients with salivary gland tumors and the clinical significances have never been reported." (PMID 26569485, 2015). "However, heparanase levels in saliva and tumor tissues of patients with salivary gland tumors and its clinical significance have not been reported." (PMID 26569485, 2015).
Salmonella Infections (1 paper, 2021). Infections with bacteria of the genus SALMONELLA. "Our results demonstrated that downregulating the protein levels of heparanase with Salmonella infection significantly reduced the migration of mouse tumor cells in vitro and in vivo." (PMID 34220326, 2021).
Shock (1 paper, 2011). The state in which profound and widespread reduction of effective tissue perfusion leads first to reversible, and then if prolonged, to irreversible cellular injury. "We have shown similar findings of syndecan-1 preservation by FFP after in vitro treatment of cells with heparanase, a syndecan-1 shedding enhancer and in animals after hemorrhagic shock." (PMID 21886795, 2011).
soft tissue sarcoma (1 paper, 2014). A malignant neoplasm arising from muscle tissue, adipose tissue, blood vessels, fibrous tissue, or other supportive tissues excluding the bones. "The primary endpoint of the current study was to check the expression of heparanase using immunohistochemistry staining of tumor samples taken from soft tissue sarcomas in adults." (PMID 24887057, 2014). "The primary goal of the current study was to examine the expression of heparanase in soft tissue sarcomas in adults according to common histological sub-types." (PMID 24887057, 2014).